CADM1 (cell adhesion molecule 1)
Diseases named in the same sentence as CADM1 in open-access papers (continued):
Sharing a sentence is not in itself a finding about the gene and the disease.
cervical cancer (continued). "Therefore, our study aimed to characterize methylation status of four host genes (RARB, CADM1, DAPK1, and PAX1) that have been studied to a great extent in relation to cervical cancer." (PMID 33718129, 2021). "In addition, this study further substantiated the previous studies results of overall high frequency of methylation rate in promoter regions of RARB, CADM1, DAPK1, and PAX1 genes in cervical cancer subjects." (PMID 33718129, 2021). "DNA methylation is known to regulate CADM1 in various tumors, such as ATLL, cervical cancer, epithelial ovarian cancer, oral squamous cell carcinoma, and breast cancer, and this epigenetic modification-targeted treatment exhibits therapeutic potential against malignancy." (PMID 33419290, 2020). "Cervical cancer and normal cervix tissue was used to select the top 5 discriminating loci among 27 loci in 4 genes (CCNA1, CADM1, DAPK1, JAM3), and one locus of JAM3 (region M4) was identified and confirmed with 267 and 224 cervical scrapings from 2 independent colposcopy referral studies." (PMID 26517242, 2015). "The cell adhesion molecule 1 (CADM1) gene, which is also known as TSLC1 or Necl-2, has been generally investigated as a tumor-suppressor gene in various tumors, including prostate, esophageal, nasopharyngeal, non-small cell lung and cervical cancers." (PMID 25845528, 2015). "In our study, we analyzed the protein and mRNA expression of CADM1 in various cervical cancer cell lines, including C33A (HPV-negative), HeLa (HPV18 positive), and SiHa and CaSki (HPV16-positive) cells, and found that CADM1 was significantly downregulated in three HPV-induced cervical cell lines." (PMID 25845528, 2015). "Various host cell methylated genes such as SOX1, PAX1, JAM3, EPB41L3, CADM1, and MAL have been investigated for predicting cervical lesions, with PAX1 gene methylation showing the most significant correlation with the progression of cervical intraepithelial neoplasia and cervical cancer occurrence." (PMID 39155349, 2024). "In combination with a specificity of 95.5% towards healthy donors (HD) and an area under the curve (AUC) of 0.872 in the receiver operating characteristic (ROC) analysis, CADM1/MAL cfDNA methylation detection might represent a novel and promising liquid biopsy marker in cervical cancer." (PMID 36010947, 2022). "Especially, the promoter methylation of the genes cell adhesion molecule 1 (CADM1) and myelin and lymphocyte protein (MAL) has been extensively studied in cervical tissue and smears and could frequently be observed in the development of cervical cancer." (PMID 36010947, 2022). "Notably, all eight genes that were frequently methylated in the HPV-transfected cell lines and cervical cancer cell lines (i.e. TP73, ESR1, RARβ, DAPK1, MGMT, CADM1, CDH13 and CHFR) overlapped with those found to be methylated in the cervical carcinoma specimens." (PMID 17971771, 2007). "CADM1 and MAL methylation was detected in seven (63.6%) and three (27.3%) of the 11 non-metastatic cervical cancer patients (FIGO IA-IIB), respectively; nine (81.8%) patients were positive for either MAL and/or CADM1." (PMID 36010947, 2022). "We observed a significant higher frequency of subjects having promoter methylation signals at the four genes, RARB (94.0%), CADM1 (76.5%), DAPK1 (64.1%), and PAX1 (96.5%), in patients with invasive cervical cancer compared to the subjects without cancer." (PMID 33718129, 2021). "Expression of CADM1 is lost or reduced in a variety of cancers, including non-small cell lung cancer (NSCLC), breast cancer, cervix cancer, and HCC." (PMID 25159494, 2014).
breast carcinoma (33 papers, 2012 to 2025). "In this study, we uncovered that the G/A heterozygotes of CADM1 (rs12286929) were associated with a decreased risk of breast cancer." (PMID 29228687, 2017). "Significant interaction between CADM1 polymorphism and high body fatness on breast cancer was observed in our study." (PMID 29228687, 2017). "Compared with CADM1 rs12286929 G/A heterozygotes with BMI < 24 group, individuals with CADM1 A/A+G/G homozygotes and BMI ≥ 24 showed increased risk of breast cancer (OR = 1.78, 95% CI: 1.32–2.40)." (PMID 29228687, 2017). "CADM1 (rs12286929) G/A genotype was found to be associated with a reduced risk of breast cancer (OR = 0.80, 95%CI: 0.64–0.99), as compared to A/A genotype." (PMID 29228687, 2017). "We also found that CADM1 has an intronic palindrome that shows significant changes in tumors and loss of CADM1 expression is associated with poor prognosis in breast cancer patients and identified as metastasis susceptibility gene in breast cancer." (PMID 28117658, 2016). "Loss of CADM1 expression is an independent prognostic factor especially associated with the development of brain metastases in breast cancer patients." (PMID 24833255, 2014). "Using a mouse model of metastatic breast cancer and complex genetic analysis, we have identified Cadm1 as a metastasis susceptibility gene." (PMID 23028344, 2012). "Similar phenomenon on breast cancer risk was observed for CADM1 polymorphism with WC and WHR." (PMID 29228687, 2017). "Results showed that the T/T genotype of RASA2 (rs16851483) was associated with increased breast cancer risk, and the G/A genotype of CADM1 (rs12286929) might play a role in reducing the risk of breast cancer." (PMID 29228687, 2017). "CADM1 is a member of an immunoglobulin superfamily and has been involved in various tumor types such as ovarian cancer, breast cancer and osteosarcoma." (PMID 38895237, 2024). "TSLC1 is highlighted as a tumor suppressor in lung adenocarcinoma, but recent studies have highlighted the metastatic suppressive properties of CADM1 in breast carcinomas." (PMID 37970212, 2023). "Contemporary studies have identified the role of CADM1 in various tumor progression, such as esophageal cancer, colon cancer, breast cancer, bladder cancer, and ovarian cancer." (PMID 33419290, 2020). "In this study, we explored the interactions between candidate SNPs of RASA2 (rs16851483), CADM1 (rs12286929) and HIF1AN (rs17094222) and body fatness for breast cancer risk." (PMID 29228687, 2017). "In this study, we investigated the association of three polymorphic sites, RASA2 (rs16851483), CADM1 (rs12286929) and HIF1AN (rs17094222), with breast cancer risk among Chinese women based on previously identified obesity-related SNPs from the GWAS study." (PMID 29228687, 2017). "This study provided a novel insight into the roles of obesity and gene polymorphisms of RASA2, CADM1 and HIF1AN in the development of breast cancer." (PMID 29228687, 2017). "As expected, epithelial genes known to be inactivated during EMT in breast cancer cells, such as Cdh1 (E-cadherin), Ocln (Occludin), Epcam, Cldn7 (Claudin 7), Id1, Krt7, Esr1, Cav2, Dsp, Gata3, and Cadm1 were among the downregulated genes." (PMID 25674539, 2015). "The prognostic role of CADM1 expression was finally verified in four large independent breast cancer cohorts (n=2136)." (PMID 24833255, 2014). "As metastasis is the primary cause of cancer-induced mortality, these findings imply a direct role for Cadm1 in metastatic progression in breast cancer and provide a link between diminished Cadm1 expression and reduced progression-free survival." (PMID 23028344, 2012). "Single-cell analysis in breast cancer has revealed that SPP1-positive tumor-associated macrophages (TAMs) display significantly increased expression of markers like apolipoprotein E (APOE), CD204, CD68, and CADM1." (PMID 39727934, 2024). "Also, CADM1 exerts its tumor-suppressor effects in breast cancer, bladder cancer, and ovarian cancer." (PMID 34497766, 2021).
breast carcinoma (continued). "Besides, previous study has found that CADM1 expression was down-regulated in different types of cancers, including gastric cancer, breast cancer, and lung carcinoma." (PMID 28904340, 2017). "It is now known that CADM1 is expressed universally in human tissues and is frequently silenced in a variety of human carcinomas, such as lung, prostate, liver, stomach, pancreatic, and breast carcinoma." (PMID 25845528, 2015). "Since metastasis is the primary determinant of overall survival in cancer, this suggests that high tumor cell Cadm1 expression may also be protective against metastasis in human breast cancer." (PMID 23028344, 2012). "Similarly, a lack of expression of the cell adhesion molecule CADM1 is associated with an advanced tumor stage, suggesting that inactivation of CADM1 promotes breast cancer development." (PMID 36078127, 2022). "PAX6 inhibits the viability, migration, and invasion of human breast cancer MCF-7 cells, whereas CADM1 inhibits insulin secretion in INS-1 cells and primary cells." (PMID 33897780, 2021). "Cell adhesion molecule-1 (CADM1), for example, suppresses development of mouse mammary tumor cell metastasis by interacting with CD8+ T cells in immune-competent hosts." (PMID 26697524, 2015). "In general, primary breast cancer and BCBM patients have low CADM1 expression." (PMID 34395444, 2021). "Moreover, CADM1 and DAL-1/4.1B methylation are involved in the invasion, metastasis, and disease progression of primary breast cancer." (PMID 34395444, 2021).
lung cancer (29 papers, 2006 to 2026). A malignant neoplasm involving the lung. "Future studies are needed to elucidate how a high proportion of shedding-susceptible CADM1 variant proteins contributes to proper spermatogenesis in testis and malignant transformation in specific types of lung cancer." (PMID 28393893, 2017). "A summary of results from different ChIP experiments showed overall enrichments of histone variants and histone modifications of nucleosomes along the Cadm1 promoter region in lung cancer cells in." (PMID 22701659, 2012). "Conversely, this result also suggested higher nucleosome occupancy associated with transcriptional repression of Cadm1 in the lung cancer cell lines." (PMID 22701659, 2012). "For instance, in lung cancer and prostate cancer, promoter methylation prevents the formation of CADM1 (also known as TSLC1)." (PMID 41476448, 2025). "In those small lung cancer cells, CADM1 specifically expresses itself in the form of a membrane-bound fragment of CADM1, which is induced by proteolytic membrane proximal cleavage of CADM1 with protease enzymes such as ADAM10 and secretase." (PMID 39156005, 2024). "The top candidate exosomal proteins associated with lung cancer, based on the number of publications supporting the association, included SPP1, CD44, ALB, SPARC, CAT, GAPDH, and CADM1." (PMID 39766023, 2024). "The bioinformatics-based association analysis identified candidate exosomal proteins associated with lung cancer, including SPP1, CD44, ALB, SPARC, CAT, GAPDH, and CADM1." (PMID 39766023, 2024). "CADM1, which was previously discovered as a tumor suppressor in lung cancer, has been revealed to be highly and exclusively expressed in HTLV-1-infected cells in the peripheral blood (PB) regardless of the ATL subtype." (PMID 36851682, 2023). "In multiple malignant tumors (HCC, ovarian cancer, lung cancer, neuroblastoma bladder cancer, etc.), high CADM1 expression inhibits malignant proliferation, invasion, and metastasis and promotes tumor cell apoptosis." (PMID 34395444, 2021). "The CADM1 gene, also known as TSLC1, was originally identified as a non–small-cell lung cancer tumor suppressor." (PMID 33155039, 2020). "TSLC1/CADM1, originally identified as a tumor suppressor in lung cancer, has recently been proposed to be a marker of malignant cells in ATL patients." (PMID 30297858, 2018). "It was also demonstrated that CADM1 expression is reduced in lung cancer cell lines and the reintroduction of CADM1 into A549, a NSCLC cell line, significantly inhibited tumorigenicity in nude mice." (PMID 25774694, 2015). "In the two lung cancer cell lines with repressed Cadm1 gene expression, H2A was also higher than H2A.Z." (PMID 22701659, 2012). "Another decorin-induced stromal gene was cell adhesion molecule 1 (Cadm1, −2.7 fold, P = 0.0011), a transmembrane glycoprotein containing Ig-like C2 modules in the ectodomain, also known as Tumor Suppressor in Lung Cancer (TSLC1)." (PMID 23029096, 2012). "Taken together, we have employed several approaches in dissecting epigenetic silencing complexity in the promoter region of the tumor suppressor gene Cadm1 in mouse lung cancer progenitor cells." (PMID 22701659, 2012). "Chromatin immunoprecipitation (ChIP) with histone variants and histone modifications also showed differences in nucleosome boundaries in two lung cancer lines that differed in Cadm1 gene expression." (PMID 22701659, 2012). "We carried out M.SssI mapping on 10 lung cancer cell lines with varying degrees of Cadm1 promoter hypermethylation and transcriptional repression, as well as a lung cancer cell line treated with 5-aza-dC." (PMID 22701659, 2012). "We showed previously that Cadm1 was repressed in mouse lung cancer progenitor cell lines, and gene expression highly correlated with promoter hypermethylation." (PMID 22701659, 2012).
lung cancer (continued). "After 5-aza-dC treatment of a lung cancer line (A2C12) that resulted in slight re-expression of Cadm1, remodeling was observed, and patterns found in normal lung became evident." (PMID 22701659, 2012). "This and previous study, found that Cadm1 promoter CpG hypermethylation correlated with transcriptional repression in lung cancer cell lines established from single, spontaneously transformed lung tumor cells of c-Myc and c-Raf double-transgenic mice." (PMID 22701659, 2012). "In this study, we sought to understand the epigenetic silencing complexity in the promoter region of Cadm1 in lung cancer progenitor cell lines established from single, spontaneously transformed lung tumors of c-Myc and c-Raf double-transgenic mice." (PMID 22701659, 2012). "We further investigated the Cadm1 promoter and thereby to gain insights into the extent of the epigenetic silencing complexity in the different lung cancer cell lines." (PMID 22701659, 2012). "For example, multiple genes in the AT1 cell program were closely related to pulmonary veno-occlusive disease (PVOD) (Bmpr2 and Eif2ak4), lung cancer (Itga9 and Braf), pulmonary fibrosis (Cadm1 and Itgb6), pulmonary hypertension (Bmpr2 and Cav1), and pulmonary emphysema (Itgb6)." (PMID 34873160, 2021). "In lung cancer, TGF-β-induced EMT confers increased tumor cell susceptibility to NK cell killing activity through the induction of E-cadherin and cell adhesion molecule 1 (CADM1) expression." (PMID 30597841, 2018). "Correspondingly, restoration of CADM1 expression in human lung cancer cell line, A549, suppressed their tumorigenicity in nude mice, whereas mutant CADM1 lacking its cytoplasmic domain, 4.1-BM, or PDZ-BM, lost its suppressor activity in subcutaneous tumor formation in nude mice." (PMID 25780926, 2015). "Our study may provide some mechanistic insights for follow-up investigations towards the regulation of Cadm1 and its role in lung cancer." (PMID 22701659, 2012). "To determine whether sequence alterations leading to variations in MNase digestions could be the cause for differential amplification efficiency, we sequenced the Cadm1 promoter region in the different lung cancer cell lines." (PMID 22701659, 2012). "Indeed, comparing DNA methylation in untreated and in aza-treated lung cancer cell line A2C12 with corresponding re-expression of Cadm1 showed that most of the 69 CpGs analyzed in the promoter region were still methylated in the aza-treated A2C12." (PMID 22701659, 2012). "We investigated the epigenetic silencing complexity in the tumor suppressor gene Cadm1 in mouse lung cancer progenitor cell lines, exhibiting promoter hypermethylation associated with transcriptional repression, but mostly unresponsive to demethylating drug treatments." (PMID 22701659, 2012). "Whether PPARg binding could have contributed to the regulation of Cadm1 in A2C12 lung cancer cell line, or have implications at all in the use of PPARg ligands, remains to be explored." (PMID 22701659, 2012). "The prognostic value related to the worse prognosis of IL-8, SCG2, NCAM1, CNTN1, CADM1, NPTX1, and APOD tumor transcripts were evaluated in seven lung cancer transcriptome datasets (validation set)." (PMID 31455042, 2019). "In addition, expression of dysfunctional CADM1 mRNAs in MCs may decrease CADM1 protein levels, downregulating their survival, and attenuating their involvement in pathogen surveillance and their anti-tumourigenic potential in lung cancer." (PMID 23063768, 2013). "In the lung cancer cell lines with little or no Cadm1 expression, results also suggested nucleosome formation (nuc 1 to nuc 5) in the predicted nucleotide positions." (PMID 22701659, 2012). "The lung cancer cell line which did not express Cadm1 (A2C12) exhibited higher values for these epigenetic modifications, and most likely that their presence contributed jointly or in parallel in the silencing of the gene." (PMID 22701659, 2012).
lung cancer (continued). "Here, we describe the collective M.SssI maps found in the lung cancer cell lines with little or no Cadm1 gene expression." (PMID 22701659, 2012). "In our study, this relationship seems also to hold true since H2A.Z occupancy was found highest in normal lung which did not display DNA methylation in the promoter region of Cadm1, and this became less in the hypermethylated lung cancer cell lines." (PMID 22701659, 2012). "Thus, treatment with 5-aza-dC alone was not able to reinstate gene expression in all the lung cancer cell lines or demethylate the promoter region of Cadm1 and these observations led us to suspect for additional layers of epigenetic silencing in place." (PMID 22701659, 2012). "After N-ChIP with the canonical histone H2A, we could amplify most expected fragments from the five predicted nucleosomes in A2C12, a lung cancer line with no Cadm1 gene expression." (PMID 22701659, 2012). "Furthermore, M.SssI maps and EMSA experiments suggested that PPARg might be binding to the Cadm1 promoter in a lung cancer cell line (A2C12), but not in normal lung." (PMID 22701659, 2012). "Furthermore, high nucleosome occupancy can be confirmed by the higher levels of ChIPed H2A in lung cancer cell lines with little or no Cadm1 gene expression, than in a cell line that still expresses the gene, as obtained in native and in formaldehyde-crosslinked chromatin." (PMID 22701659, 2012). "EMSA results suggested that PPARg bind in vitro to the Cadm1 promoter with nuclear extracts from the lung cancer cell line (A2C12), but not in normal lung, and could play a role in lung cancer." (PMID 22701659, 2012).